SCNN1B (sodium channel epithelial 1 subunit beta)
Diseases named in the same sentence as SCNN1B in open-access papers (continued):
Sharing a sentence is not in itself a finding about the gene and the disease.
SCNN1B also shares sentences with these, for which no sentence is quoted: renal cell carcinoma (3 papers); essential hypertension (2); Hypokalemia (2); inflammation (2); adenocarcinoma (1); Central diabetes insipidus (1); childhood-onset schizophrenia (1); chronic kidney disease (1); chronic lung disease (1); colon cancer (1); diabetes insipidus (1); diabetes mellitus type 2 (1); eosinophilia (1); haematological diseases (1); hyponatraemia (1); Liddle syndrome 1 (1); malignant glioma (1); nephrogenic diabetes insipidus (1); preeclampsia (1); primary ciliary dyskinesia (1); pseudohypoaldosteronism type 1 (1); pulmonary fibrosis (1); restrictive lung disease (1); rheumatoid arthritis (1); stomach cancer (1); Ureteral obstruction (1).